LTB (lymphotoxin beta)
Diseases named in the same sentence as LTB in open-access papers (continued):
Sharing a sentence is not in itself a finding about the gene and the disease.
alveolar rhabdomyosarcoma (1 paper, 2021). A rapidly growing malignant mesenchymal neoplasm. "Additionally, PAX5, LTB and CD44 (markers of stem cells) were significantly colocalized in the scRNA-seq data of the human alveolar rhabdomyosarcoma cell line Rh41." (PMID 33397394, 2021).
arteritis (1 paper, 2018). An inflammatory process affecting an artery. "There was only a moderate correlation between active tubulitis/interstitial inflammation (atii) and the expression level of Ltβ mRNA (p<0.05) and active arteritis (av) and the expression of the LTβR mRNA (p<0.05) when patients from all groups were analyzed together." (PMID 29300739, 2018).
autoimmune pancreatitis (1 paper, 2024). "Meanwhile, according to a study conducted on autoimmune pancreatitis (AIP), a common feature in IgG4-RD, it is observed that LTα and LTβ are overexpressed and positively correlate with CXCL13 expression." (PMID 38911857, 2024).
cerebral malaria (1 paper, 2008). A sequestration of Plasmodium falciparum in the brain, which can cause coma and/or seizures. "Interestingly, the strong increase in brain CD8+ T cells seen in wild type or TNF deficient mice that develop cerebral malaria was essentially absent in PbA-infected LTβR or LTβ deficient mice." (PMID 18612394, 2008).
co-infection (1 paper, 2016). "The current study involving more HIV+ individuals demonstrates that detectable immune response of PPD-specific CD8+ T cells appears to be one of surrogate markers for M. tb co-infection including LTB and ATB in HIV-1-infected humans as HIV+TB- group exhibits no or few PPD-specific CD8+ T cells." (PMID 26959228, 2016).
endometriosis (1 paper, 2024). The growth of functional endometrial tissue in anatomic sites outside the uterine body. "In the high JUP group, we identified several downregulated genes in the PBMCs from endometriosis patients, including HBB, HBA1, HBA2, RGPD2, CH25H, LTB, IFIT2 and JUN." (PMID 39684780, 2024). "Among these genes, three (RGPD2, LTB, and KLRC1) exhibited distinct expression profiles between control and endometriosis-derived PBMCs." (PMID 39684780, 2024).
experimental autoimmune encephalomyelitis (1 paper, 2021). An autoimmune demyelinating disease of the central nervous system that is produced experimentally in animals by the injection of homogenized brain or spinal cord in Freund's adjuvant. "The combination of IL-17 production and LTB signaling has been associated with the induction of meningeal resident tertiary lymphatic tissue in experimental autoimmune encephalomyelitis (EAE) in mice, implicating these pathways in the seeding of immune cell accumulations in MS." (PMID 33748804, 2021).
fibrosarcoma (1 paper, 2022). A malignant mesenchymal fibroblastic neoplasm affecting the soft tissue and bone. "Notably, we characterized a Treg-tumor cell-specific interaction mediated by the ligand Lymphotoxin Beta (LTB) and its receptor lymphotoxin beta receptor (LTBR), which is required for fibrosarcoma and hepatocellular carcinoma tumor formation." (PMID 35853872, 2022).
gastric cancer (1 paper, 2021). A primary or metastatic malignant neoplasm involving the stomach. "Likewise, the expression of LTβ, a ligand which is crucial for activation of the non-canonical NF-κB pathway upon H. pylori infection, was lower in MKN45 gastric cancer cells infected with HopQ mutant strains compared to expression in cells infected with wild type bacteria." (PMID 34442827, 2021).
gastritis (1 paper, 2019). Inflammation of the stomach. "According to the gastritis grading scores, NZ-Δsp-napA group displayed the lowest inflammation level among the H. pylori challenged groups, whereas the NapA+LtB immunized mice had significantly higher inflammatory lesion than the mice treated with NapA alone (p < 0.05)." (PMID 31461854, 2019). "Notably, NZ-Δsp-napA+ltB group showed much more severe gastritis than NZ-Δsp-napA group." (PMID 31461854, 2019).
glioblastoma (1 paper, 2022). The most malignant astrocytic tumor (WHO grade IV). "Apart from higher numeric abundance, cells from R glioblastomas showed significantly higher transcript abundances of LTB compared to their ND glioblastoma-associated counterparts." (PMID 36230839, 2022). "Mining of the Cancer Genome Atlas Consortium (TCGA) and the Chinese Glioma Genome Atlas (CGGA) glioblastoma cohorts showed enhanced LTB expression in MES-like glioblastomas and an association of LTB expression levels with overall survival." (PMID 36230839, 2022). "In summary, single-cell RNA-sequencing data from human ND and R glioblastomas showed an accumulation of NK cells with reduced expression of activation, interferon-gamma and cell cycle genes and enhanced expression LTB and apoptosis-associated genes, suggesting an exhausted NK cell phenotype." (PMID 36230839, 2022). "To assess the impact of LTB expression on the clinical outcome of glioblastomas, we compared overall survival in low- and high-LTB expressing samples of both datasets with the median as the cutoff." (PMID 36230839, 2022). "In human glioblastoma tissues, LTB expression was spatially correlated with the MES-like subtype, and neurodevelopmental gene expression signatures appeared to be associated with prognosis." (PMID 36230839, 2022). "Its ligand LTB was undetectable in glioblastoma sections due potentially to the challenges of detecting secreted proteins in immunohistochemistry." (PMID 36230839, 2022). "High LTB gene expression was mainly associated with MES-like and neurodevelopmental glioblastoma subtypes." (PMID 36230839, 2022). "Next, we utilized a spatial transcriptomics dataset of human glioblastomas to map LTB and LTBR expression in situ." (PMID 36230839, 2022). "Likewise, LTB expression across the immune cell types was enhanced in R glioblastomas." (PMID 36230839, 2022).
glioma (1 paper, 2022). A benign or malignant brain and spinal cord tumor that arises from glial cells (astrocytes, oligodendrocytes, ependymal cells). "In summary, during glioma progression, NK cells appear to be increasingly involved in LTB-mediated crosstalk with myeloid cells and likely other non-immune cells that are not present in this dataset." (PMID 36230839, 2022).
glomerulonephritis (1 paper, 2018). A renal disorder characterized by damage in the glomeruli. "As in kidneys with various forms of glomerulonephritis, expression of LTβ was observed in infiltrating mononuclear inflammatory cells diffusely within the tissue or in follicular or follicular-like infiltrates." (PMID 29300739, 2018). "In a previous study, we have also observed LTβ expression in TECs in biopsies from kidneys with different forms of glomerulonephritis." (PMID 29300739, 2018).
idiopathic inflammatory myopathies (1 paper, 2024). "In a study focused on idiopathic inflammatory myopathies, a robust upregulation of LTβ was observed in regenerating muscle fibers." (PMID 39193020, 2024).
ileitis (1 paper, 2024). "Recipients of 10%/90% mixtures of LTα−/−/μMT-TNFΔARE/+ and LTβ−/−/μMT-TNFΔARE/+ BM should also be impacted by TNFΔARE/+ induced ileitis, but for these mixtures, all B cells would lack either LTa or LTb." (PMID 38464070, 2024). "Both groups of mice had similar neutrophil and T cell Infiltration into the ileum, suggesting that loss of LTb in B cells or consequent loss of TLS did not substantially impact the inflammatory component of ileitis." (PMID 38464070, 2024).
leukemia (1 paper, 2017). A malignant (clonal) hematologic disorder, involving hematopoietic stem cells and characterized by the presence of primitive or atypical myeloid or lymphoid cells in the bone marrow and the blood. "Finally, altered expressions of CD28, CCR7, CX3CR1, IFNG, LTB and PRF1 were all contributing to the inflammatory profile of the TCRγδ+ T-LGL leukemias." (PMID 28407008, 2017).
lupus nephritis (1 paper, 2021). Glomerulonephritis in the context of systemic lupus erythematosus. "Interestingly, a high expression of Lymphotoxin Beta (LTB) genes was found in IgAN and lupus nephritis." (PMID 34674036, 2021).
malaria (1 paper, 2010). Malaria is a serious and sometimes fatal disease caused by a parasite that commonly infects a certain type of mosquito which feeds on humans. "Lack of association between LTA/TNF/LTB SNPs and severe malaria subgroups when compared with adult and childhood controls in the Papuan population." (PMID 21029472, 2010).
pancreatic ductal adenocarcinoma (1 paper, 2023). An infiltrating adenocarcinoma that arises from the epithelial cells of the pancreas. "Lastly, cluster #8 (i.e., PP-4) was enriched in inflammatory and EMT-inducing markers, often associated with pancreatitis and pancreatic ductal adenocarcinoma, such as LTB, IL32, and AREG." (PMID 37649117, 2023).
papillary thyroid carcinoma (1 paper, 2021). "In papillary thyroid carcinoma, upregulated LTB also triggered metastasis." (PMID 33397394, 2021).
primary immunodeficiency (1 paper, 2019). "Enrichment Kyoto Encyclopedia of Genes and Genomes (KEGG) analysis revealed DEGs engaged into three metabolic pathways: NF-kappa B signaling pathway (ZAP70, LCK, LTB), T cell receptor signaling pathway (ITK, ZAP70, LCK), and primary immunodeficiency (ZAP70, IL7R, LCK)." (PMID 30917529, 2019).
rhabdomyosarcoma (1 paper, 2021). A rare aggressive malignant mesenchymal neoplasm arising from skeletal muscle. "In cell cycle analysis, rhabdomyosarcoma cells with high expression of PAX5 and LTB were significantly located in the G2M and S phases." (PMID 33397394, 2021).
tumor (46 papers, 2012 to 2026). "AHNAK2 and SLC2A1 were primarily expressed in epithelial cells, while CD27 and LTB were predominantly associated with T cells, potentially influencing tumor immunity." (PMID 39593730, 2024). "NF-κB signaling driven by lymphotoxin beta expression is associated with tumor regression in TNBC mouse models." (PMID 39623404, 2024). "In humans, enhanced LTB expression was primarily associated with MES-like tumor transcriptional subtypes that show strong transcriptional similarities with the GL261 cell line." (PMID 36230839, 2022). "AKT/CAT-transformation of hepatocytes and subsequent LTβ/LTβR upregulation are thus implicated in tumour proliferation and progression." (PMID 26206664, 2016). "To determine if LTβ upregulation is associated with activation of NF-κB signaling in the FL-N/35 tumors, we first investigated RelA (p65) localization in livers of tumor-bearing animals." (PMID 23555249, 2013). "The involvement of LTβ and genes responding to LTβR signaling, such as CXCL13, suggest an active role of the LTβ–LTβR pathway in tumor-associated endothelium and lymphoid organogenesis as previously reported." (PMID 40897896, 2025). "In parallel, the other four pro‐tumour molecules showed a consistent pattern similar to TNF‐α or LTβ." (PMID 37997519, 2023). "The mRNA levels of proinflammatory/pro‐tumour cytokines were measured by qRT‐PCR, and the induction of TNF‐α and Ltβ strikingly correlated with tumour development in the CLI Fah−/− mice." (PMID 37997519, 2023). "LTA and LTB interact as part of their role in innate immunity, where they help prevent tumor growth." (PMID 36425073, 2022). "LTB (lymphotoxin β) is a tumor necrosis factor (TNF)-related cytokine that initiates extrinsic apoptotic cell death in tumor cells via the LTβR signaling pathway." (PMID 32513298, 2020). "It is conceivable, oncogenic activation is intrinsically regulating LTβ induction due to immense transcriptional amplification following transformation, or mediated from extrinsic factors in the tumour milieu." (PMID 26206664, 2016). "We provide evidence that AKT/CAT combined activation can mediate the upregulation of LTβ/LTβR expression and further demonstrate LTβR signalling is a central activator during tumour development." (PMID 26206664, 2016). "AKT/β-catenin-transfected livers displayed increased expression of LTβ and LTβR, with antagonism of LTβR signalling reducing tumour progression and enhancing survival." (PMID 26206664, 2016). "Tumor-specific augmentation of LTβ expression was confirmed at the protein level, while immunofluorescence staining showed that hepatocytes were the major source of this cytokine." (PMID 23555249, 2013). "Lymphotoxin-α (LTα) and LTβ can be expressed by T-cells and function as a mediator of tumor cell death through the LTβR." (PMID 22389673, 2012). "Except for genes that might have been highly expressed in the lymph nodes (CCL21, LTB) and has already previously identified related to tumor metastasis gene (MMP9), we selected GPNMB as target gene for further study." (PMID 38706915, 2024). "Moreover, we found a significantly higher positive regression coefficient between CD8A expression and TNF‐α or LTβ in adjacent tumour tissues than in HCC tissues and normal tissues." (PMID 37997519, 2023). "The roles of different mediators, which include Toll-like receptors, lymphotoxin beta (LTB), intercellular adhesion molecule 1 (ICAM1), interferon beta, chemokines, and cytokines, are linked to the NF-κB activation and promotion of tumor regression, leading to better disease prognosis." (PMID 36518665, 2022). "Additionally, LTB itself can induce EMT, which is the core mechanism of tumor invasion and metastasis; loss of cell-to-cell contact via epithelial cells enables tumor migration." (PMID 36567723, 2022). "LTBR interacted with lymphocyte LTB and promoted tumor cell metastasis." (PMID 34805166, 2021).
tumor (continued). "Tregs secrete lymphotoxin beta (LTB), engaging with lymphotoxin beta receptor (LTBR) on MCs and influencing tumor progression." (PMID 41035074, 2025). "For example, strong interactions existed between the tumor cells and B cells, CD4+ T cells, CD8+ T cells or Tregs through the lymphotoxin and lymphotoxin beta receptor (LTB-LTBR)." (PMID 38191598, 2024). "Among tumor-related genes characterizing Clusters I and II, differences in the levels of DNA methylation and mRNA expression for the SPHK1, INHBA, LTB and PDE3B genes were correlated with poorer tumor differentiation." (PMID 36348017, 2023). "In our present set of tissue samples, differences in DNA methylation levels resulting in differences in the mRNA expression levels of the SPHK1, INHBA, LTB and PDE3B genes were correlated with poorer tumor differentiation." (PMID 36348017, 2023). "Major initiators of tumor inflammation such as CCL2, CXCL1, CXCL2, CXCL11, CSF1, LTB, and TNFSF10 were found to increase in both cell lines, while inflammation suppressors like IL13and IL1RN were decreased." (PMID 36831395, 2023). "We found that transcripts of LTB and its receptor LTBR are found in adjacent tumor regions with overlaps at the intercept of these regions." (PMID 36230839, 2022). "The five TNFSF ligand transcripts were differentially expressed by all these subsets, with tumor-infiltrating germinal cells expressing the highest levels of TNF, LTA, TNFSF10 and LTB, and tumor-infiltrating plasma cells expressing the highest levels of FASLG." (PMID 35392082, 2022). "Frequent loss-of-function mutations were also observed for CD58, IGLL5, IRF1, LTB, MGA and VMP1 in blood cancers, implicating a potential tumour-suppressive role of these genes in the pathogenesis in this tissue type." (PMID 33420369, 2021). "So, the tumor suppressing and encouraging functions of NF-κB manifest a curiosity wherein the activities of Toll like receptors (TLRs), intercellular adhesion molecule 1 (ICAM-1) and lymphotoxin beta (LTB) assume significance." (PMID 37970206, 2023). "characterized “tumor-matching” T cells in the peripheral blood (i.e., T cells in the blood expressing tumor-specific TCRs) as cells that expressed a more effector phenotype with a decreased expression of genes GYPC, CCR7, LTB, and FLT3LG." (PMID 37122719, 2023). "LTB also plays a role in mediating RELB and nuclear factor-κB-2, components of the alternative nuclear factor-κB pathway; this alternative pathway promotes tumor cell migration that is an important feature of metastasis." (PMID 36567723, 2022). "In addition, LTB, IL1A, LY9, and SLAMF7 were differentially expressed between normal and tumour tissues." (PMID 33397394, 2021). "Among them, LTB resulted completely absent in non-tumour ducts, while variable expression was found in cancer epithelial cells." (PMID 35201443, 2021). "Simonin et al32 recently elucidated a HCV-mediated mechanism that directly regulates tumour-specific increases in LTβ, independent of the oncogenic driver, N-MYC." (PMID 26206664, 2016). "LTB is the β-chain of the heteromeric complex of surface lymphotoxin (LT), which binds to the LT-β receptor (LTBR), and ligand-receptor binding between the two activates NF-κB, affects the inflammatory microenvironment of tumors, and correlates with tumor progression." (PMID 38644411, 2024). "In the subsequent analysis of the potential pathways between GrB+ B cells and tumor cells, the most important incoming and outgoing L-R pairs were the signaling complexes, macrophage migration inhibitory factor (MIF) -(CD74 + CXCR4) and lymphotoxin-alpha (LTA)–(LTB + LTBR), respectively." (PMID 38386050, 2024). "We found that the correlation of expression for CLIC6 and RAB30 in neighboring cells is higher in the ER+/PR+ group, while the correlation of expression for KLRD1 and LTB is higher in the ER‐/PR‐ group, regardless of whether the tumor is detected in the early or late stage." (PMID 40420636, 2026).
tumor (continued). "Thus, based on the results of this study, we could determine the transcriptional regulatory pattern between LTB and PAX5 and their cellular colocalization in cancer cells, and whether this regulatory mechanism existed in tumour-infiltrating B cells and plasma cells needs to be further validated." (PMID 33397394, 2021). "In contrast, members of the TNF receptor superfamily (TNFSF), which mediate the noncanonical NF-κB pathway, a potential tumor-promoting mechanism (NCR3, CD40LG, LTA, LTB, and TNFRSF13C), were observed in East Asian and Mixed ancestry populations (TCGA)." (PMID 41387728, 2025).